NOX4 (NADPH oxidase 4)
Diseases named in the same sentence as NOX4 in open-access papers (continued):
Sharing a sentence is not in itself a finding about the gene and the disease.
Hyperglycemia (continued). "Furthermore, losartan attenuated the renal expression of NOX4, which was induced by hyperglycemia." (PMID 30420805, 2018). "In MetS, hyperglycemia and dyslipidemia activate NADPH oxidase (NOX) enzymes, particularly NOX2 and NOX4, in endothelial cells, adi-pocytes, and vascular smooth muscle cells." (PMID 40722947, 2025). "NADPH oxidase 4 (NOX4) plays a central role in ROS production, particularly in DKD, where hyperglycemia-induced NOX activation contributes to oxidative damage in renal tissues, thereby exacerbating fibrosis and cellular apoptosis." (PMID 39702603, 2024). "Another report shows hyperglycemia upregulates NOX1, NOX2, NOX4, and iNOS expression in VSMC and cell migration." (PMID 39765782, 2024). "In conclusion, PPARβ/δ activation confers vascular protection against hyperglycemia-induced oxidative stress by suppressing NOX-2 and NOX-4 expression plus a direct induction of HO-1; with the subsequent downregulation of the Nrf2 pathway." (PMID 30046379, 2018). "Hyperglycemia induces NOX4, p22phox, p47phox, but not NOX1 or NOX2, selectively in the renal cortex." (PMID 39765782, 2024). "One question which remains to be solved is the lack of NOX4 mRNA level changes by hyperglycemia in our model, despite changes on the protein level." (PMID 36829947, 2023). "Nox4 also regulates VEGF expression under conditions of oxidative stress and hyperglycemia." (PMID 34063668, 2021). "In HMVEC, gene expression of SOD1 and SOD2 (non-significant) simultaneously increased with O2 ̅ levels, and CYBA (non-significant), NOX1, and NOX4 expression during hyperglycemia." (PMID 24093550, 2013). "NOX-4 is a membrane-bound enzyme present in a dissociated form in a resting state and becomes assembled into a functional oxidase complex upon stimulation and generates superoxide free radical by transferring one electron to oxygen from NADPH during prolonged hyperglycaemia." (PMID 39166118, 2024). "However, the mechanism on how CCN1 is regulated by hyperglycemia or hyperlipidemia and how CCN1 regulates NOX4 expression remains unclear." (PMID 34458333, 2021). "In support of a link between hyperglycemia and NOX1, only mRNA and protein expression of NOX1, but not NOX2 or NOX4, increased with high glucose." (PMID 31382355, 2019).
pancreatic cancer (47 papers, 2011 to 2025). "This suggests that NOX4-associated lncRNA plays an important role in the immune microenvironment of pancreatic cancer." (PMID 36874093, 2023). "In cachectic muscles, tumor-induced SIRT1 loss leads to the activation of NF-κB, which upregulates NOX4 expression to exaggerate pancreatic tumor-induced cachexia." (PMID 35646942, 2022). "Our experiments demonstrated NOX4 overexpress or inhibition in pancreatic cancer cells caused changes of invasion and metastatic ability." (PMID 33499904, 2021). "Other cancers that associate with NADPH oxidase NOX4 include prostate cancer, pancreatic cancer, and urothelial carcinoma." (PMID 29478325, 2019). "Among the different NOX isoforms, NOX 2 and 4 when deregulated have been associated with cancer; particularly, NOX4 overexpression has been shown in different types of cancers, such as renal and pancreatic cancers, and in glioblastoma and invasive breast cancers." (PMID 34205678, 2021). "For example, ROS induced by 5-lipoxygenase (5-LO) and NADPH oxidase 4 (NOX4) significantly augment pancreatic cancer cell survival." (PMID 40563367, 2025). "This study shows that NOX4 are suitable biomarkers for pancreatic cancer, and the lncRNAs influenced by NOX4 is closely related to the prognosis of patients." (PMID 36874093, 2023). "Exploring the role played by NOX4-related lncRNAs in pancreatic cancer is pioneering and meaningful." (PMID 36874093, 2023). "Previous research gas determined that NOX4 has an effect on tumor metabolism, and a correlation between NOX4 expression and glycolysis can be observed in lung, prostate, and pancreatic cancers 26-28." (PMID 37670970, 2023). "As a mature tumor marker, NOX4-related lncRNAs provide new research strategies for prognostic evaluation, molecular mechanism and clinical treatment of pancreatic cancer." (PMID 36874093, 2023). "Firstly, NOX4 expression in pancreatic cancer tissues under different pathological conditions was detected by applying immunohistochemical staining of tissue microarray (TMA)." (PMID 36874093, 2023). "NOX4 is involved in the development of pancreatic cancer in various forms, mediating the activation of signaling molecules in multiple pathways and altering cellular activity in the tumor microenvironment." (PMID 36874093, 2023). "We first analyzed the levels of NOX4 expression in pancreatic tumors and normal tissues from TCGA and GTEx databases, and found that NOX4 was overexpressed in the tumor tissues." (PMID 36874093, 2023). "H-Score was used to evaluate the effect of NOX4 on the survival rate of patients with pancreatic cancer in each clinical characteristic subgroup." (PMID 36874093, 2023). "Studies have found that NOX4 supports apoptosis of malignant pancreatic cancer cells by increasing Reactive oxygen species (ROS) levels and DNA damage." (PMID 36874093, 2023). "And the results of this study suggest that NOX4-related lncRNAs seem to exhibit more obvious results than NOX4 in pathological analysis and individual diagnosis for pancreatic cancer patients in different states." (PMID 36874093, 2023). "According to the validation of a public database, we found that NOX4 was highly expressed in tumor tissues, and high expression of NOX4 predicts poor prognosis in patients with pancreatic cancer." (PMID 36874093, 2023). "This proves that NOX4 can be more quickly applied as a marker for the diagnosis and treatment of pancreatic cancer on clinical trials." (PMID 36874093, 2023). "The use of techniques such as liquid biopsy in clinical diagnosis makes it possible to validate the diagnosis of pancreatic cancer based on NOX4-related lncRNAs." (PMID 36874093, 2023). "This indicates that the related lncRNAs score based on NOX4 has a new explanation for the mechanism of drug resistance in pancreatic cancer and can well predict the chemotherapy response." (PMID 36874093, 2023).
pancreatic cancer (continued). "In this study, the expression of NOX4 in pancreatic cancer tissues was detected by immunohistochemical staining of tissue microarrays, and their effects were confirmed." (PMID 36874093, 2023). "This study evaluated the prognosis of patients with pancreatic cancer based on the validated pancreatic cancer markers (NOX4) and NOX4-related lncRNA under subgroups of clinical indicators and to explore their relationship with the immune microenvironment." (PMID 36874093, 2023). "At the same time, we found that the relationship between NOX4 and lncRNAs in pancreatic cancer has rarely been studied, and the functions of NOX4-related lncRNAs in the tumor microenvironment and immune microenvironment have rarely been explored." (PMID 36874093, 2023). "NOX4 also links pancreatic cancer metabolic regulation to endoplasmic reticulum redox vulnerability." (PMID 37626693, 2023). "During the invasion of pancreatic cancer, NOX4 induces epithelial-mesenchymal transformation through Rac/p38 MAPK related pathway, and up-regulates E-cadherin through transforming growth factor-β pathway to promote cell migration." (PMID 36874093, 2023). "The NOX4 expression level directly reflects the ROS level in pancreatic cancer cells and in our study, both elevated ROS and NOX4 expression were found in higher glucose concentration groups." (PMID 36211828, 2022). "NADPH oxidase 4 (NOX4) is an enzyme that increases the invasiveness and metastasis of pancreatic cancer cells." (PMID 35625561, 2022). "NOX4 has been described before in the pancreatic cancer section, and it is regulated by hypoxia and TGF-β; NOX4 regulates the expression of NRF2." (PMID 35625561, 2022). "In oncogenic RAS-driven human pancreatic tumors and in pancreatic cancer mouse models, the levels of the ROS-inducing NOX4 correlate positively with tumor progression, indicating a heightened reliance on ROS during tumorigenesis." (PMID 35147163, 2022). "Loss of Sirtuin 1 (SIRT1) induces NF-κB signaling in cachectic muscles, activating the expression of FOXO and NADPH oxidase 4 (Nox4), which trigger protein degradation pathways in pancreatic cancer." (PMID 36077789, 2022). "Nox4 has previously been reported to enhance Akt activation in other cell types, such as adipocytes, pancreatic cancer cells, HEK293 cells, and vascular smooth muscle cells." (PMID 31821410, 2021). "In pancreatic cancer, Nox4 is one of the primary sources of ROS, as TGF-β stimulates Nox4 gene expression together with a ROS increase, even though a decrease in Nox4 lowers ROS synthesis." (PMID 34947978, 2021). "This review summarizes the potential roles and its mechanism of NOX4 in pancreatic cancer and explores NOX4 as the potential therapeutic target in pancreatic cancer." (PMID 34930338, 2021). "More importantly, recent studies illuminate that NOX4 promotes pancreatic cancer occurrence and development in different ways." (PMID 34930338, 2021). "NOX4-derived ROS has been reported responsible for TGFβ induced pancreatic cancer cell chemotaxis via NOX4/ROS/p38 MAPK cascade." (PMID 33941245, 2021). "In the case of renal and pancreatic cancers and invasive breast cancers, the overexpression of Nox4 has been demonstrated." (PMID 34947978, 2021). "It has been confirmed that NOX4 is highly expressed in many types of tumor cells such as pancreatic cancer, renal cell carcinoma and gastric cancer." (PMID 33153467, 2020). "NOX4 is localized at the cell membrane and NOX4-produced ROS is considered an important redox signal transducer in TGFβ-induced EMT in pancreatic cancer and glioblastoma cells." (PMID 31822964, 2020).
pancreatic cancer (continued). "81.7% (98/120) of the pancreatic cancer tissues exhibited high levels of NOX4, whereas only about 35.5% (39/110) of the pancreatic tissues with normal histological appearance were positive for NOX4 expression." (PMID 28232723, 2017). "Insulin-like growth factor I has been reported to activate NOX4 through transcriptional upregulation of p22phox via an Akt-dependent pathway in pancreatic cancer cells." (PMID 28232723, 2017). "Our results revealed that NOX4 is required for PDAC development and pharmacologic targeting of NOX4 represents a potential novel therapeutic approach for pancreatic cancer." (PMID 28232723, 2017). "Hiraga and coworkers reported that NOX4 was up-regulated in pancreatic cancer, and contributed to TGF-beta-induced epithelial-mesenchymal transition." (PMID 26330360, 2015). "The role of Nox4 has also been confirmed in pancreatic cancer cells, where blocking of Nox4 impaired TGF-β-induced EMT." (PMID 26078812, 2015). "NOX4 levels are increased in a genetically defined mouse model of Ras-induced pancreatic cancer, as well as in human pancreatic tumors, which are known to exhibit aggressive growth." (PMID 24583638, 2014). "Many observations point to a critical role of NOX4 in apoptosis resistance and sustained tumor cell proliferation in various types of cancer cells including glioma cells and pancreatic cancer cells." (PMID 24946933, 2014). "We show that Nox4 expression is upregulated in human pancreatic tumor samples and in a genetically defined murine model of Ras-driven pancreatic cancer, where increased ROS levels can be visualized in situ." (PMID 24583638, 2014). "The additional observation of a strongly synergic effect of NOX4 inhibition and DNA damage generation by gemcitabine on a pancreatic cancer cell line points to a potential translational value of our findings that deserves further exploration." (PMID 24583638, 2014). "For example, NOX4 has been shown to protect pancreatic cancer cells from apoptosis and mediate proliferation and survival of pancreatic cancer cells." (PMID 24946933, 2014). "prognosis-related NOX4-related lncRNAs and NRlncSig Score were finally obtained by univariate and multivariate Cox regression with Least Absolute Shrinkage and Selection Operator (Lasso) analysis in pancreatic cancer patients." (PMID 36874093, 2023). "In pancreatic cancer cells under hypoxia, NOX4 expression is upregulated." (PMID 36902253, 2023). "And combined with the public database, the expression of NOX4-related lncRNAs in human pancreatic cancer was analyzed to explore their relationship with prognosis and immune microenvironment of patients with pancreatic cancer, immune cells and immune status were explored respectively." (PMID 36874093, 2023). "Finally, more in vitro and in vivo studies are needed to demonstrate the mechanism of NOX4-related lncRNAs in pancreatic cancer." (PMID 36874093, 2023). "To better understand the relationship of NOX4 gene expression in pancreatic cancer, we downloaded RNA-seq data from the TCGA database of 182 pancreatic cancer patients, the patients were divided into high-expression group and low-expression group according to the median expression of NOX4 genes." (PMID 36874093, 2023). "Moreover, the differential NOX4 expression in pancreatic cancer patients seems to affect the expression of immune cells." (PMID 36874093, 2023). "Among the NOX family members, NOX4 is the most often overexpressed NOX isoform associated with cancer; it has been observed in a number of solid tumors, including colorectal cancer (CRC), pancreatic cancer, glioblastoma, and prostate cancer." (PMID 37626693, 2023).
pancreatic cancer (continued). "Furthermore, TGF-β has been demonstrated to induce NOX4 gene expression in crosstalk with an increase in ROS production, while NOX4 is downregulated with reduced ROS synthesis, thus indicating, in pancreatic cancer cells, that NOX4 is the main source of ROS." (PMID 34205678, 2021). "Depletion of NOX4 can induce apoptosis in pancreatic cancer cells through the AKT–ASK1 pathway." (PMID 28422720, 2017). "Finally, we report the exciting finding that specific NOX4 small-molecule inhibitors act synergistically with a first-line chemotherapeutic agent (gemcitabine) in a human pancreatic cancer cell line." (PMID 24583638, 2014). "Finally, in cancer we show that Nox4 is increased in both human tumors and a mouse model of pancreatic cancer and specific Nox4 small-molecule inhibitors act synergistically with existing chemotherapic agents." (PMID 24583638, 2014). "Various studies have been carried out on the role of NOX4 in pancreatic cancer progression." (PMID 22032647, 2011). "NOX4 was upregulated in pancreatic cancer and was involved in the development of pancreatic cancer by promoting cell proliferation, regulating cell metabolism, and mediating angiogenesis, suggesting NOX4 was a potential therapeutic target for pancreatic cancer." (PMID 36915111, 2023). "To further validate these findings in independent cohorts, we scrutinized the Oncomine database and observed increased Nox4 mRNA levels not only in several PCa studies but also in other tumor types, particularly those with a prominent stromal component such as breast, gastric and pancreatic cancer." (PMID 29441570, 2018). "In addition, TGF-β was shown to induce NOX4 gene expression along with ROS increase, while the downregulation of NOX4 reduced ROS synthesis, indicating that Nox4 is one of the main sources of ROS in pancreatic cancer cells." (PMID 26078812, 2015). "Previous studies have shown that NOX4 has the potential to promote the progression of non-small cell lung cancer (NSCLC), colorectal cancer, and pancreatic cancer while CYBB has been approved to enhance the metastasis of melanoma in mice." (PMID 39000203, 2024). "It was found that the survival rate of pancreatic cancer cells significantly increased after stimulation with high levels of ROS triggered by 5-lipoxygenase (5-LO) and NADPH oxidase 4 (Nox4)." (PMID 38474405, 2024). "NOX4 regulates SNAIL1 transcription to induce EMT and promote the invasion and metastasis of pancreatic cancer cells." (PMID 36902253, 2023). "The knockdown or pharmacological inhibition of Nox4 activity abolishes tumor-induced cachexia in mice, suggesting that targeting the SIRT1-Nox4 axis in muscles mitigates cachexia in pancreatic cancer." (PMID 36077789, 2022). "Nicotinamide adenine dinucleotide phosphate (NADPH) oxidase 4 (NOX4) is one of the seven isoforms of NOX family, which is upregulated in pancreatic cancer cell, mouse model of pancreatic cancer and human pancreatic cancer tissue." (PMID 34930338, 2021). "For example, NOX4 is Smad3-regulated in breast cancers, and it provides ROS sources for the EMT phenotype switch in pancreatic cancers." (PMID 33941245, 2021). "Most importantly, it has been recently shown that in a cachectic mouse models of pancreatic cancer, resveratrol is able to restrain muscle mass and strength by reducing the SIRT1-NOX4 signaling in muscle, being NOX4 a key modulator of ROS production." (PMID 33255345, 2020). "In pancreatic cancer models, H-RASV12 oncogene induces ROS production in RAC1 and NADPH oxidase NOX4-dependent manner." (PMID 29478325, 2019). "Genetically suppression of NOX4 expression or pharmacologic targeting NOX4 using DPI leads to metabolic disruption and decreases pancreatic cancer growth in vitro and in vivo." (PMID 28232723, 2017).
pancreatic cancer (continued). "Previous studies reported that inhibition of NOX4 is sufficient to activate apoptosis via PI3K/Akt pathway in pancreatic cancer PANC-1 cells, and NOX4 mediates many cellular effects in various types of normal cells." (PMID 24946933, 2014). "ROS generated by NOX4, was partly depleted by NS1, which likely led to apoptosis in melanoma cells as observed in pancreatic cancer cells." (PMID 25296975, 2014). "DEGs based on NOX4 expression does not seem to adequately explain the important role of NOX4 in the tumor microenvironment of pancreatic cancer." (PMID 36874093, 2023). "To date, NOX4 has been observed to participate in multiple malignancies, including lung cancer, renal cell cancer (RCC), colorectal cancer (CRC), gastric cancer (GC), pancreatic cancer, glioblastoma, and ovarian cancer, etc." (PMID 35646942, 2022). "Moreover, the NOX4 expression in pancreatic cancer cells did not showed an obvious change after being treated with 100 U MMP-3 in the GSE50931." (PMID 36211828, 2022).